KCNS2 (potassium voltage-gated channel modifier subfamily S member 2)
Description:
Each regulatory subunit has unique regulatory properties that can lead to extensive inhibition, significant changes in kinetics, and/or substantial shifts in the voltage dependencies of the inactivation process.
Synonyms: Kv9.2
Tractability: Small molecule: an approved drug acts on it; it belongs to a druggable protein family. Antibody: its Gene Ontology location is reachable by antibodies, with high confidence; UniProt places it where antibodies can reach, with medium confidence; UniProt predicts a signal peptide or a membrane-spanning region.
Gene: Protein-coding gene on chromosome 8 (98,426,958 to 98,432,853, forward strand). Ensembl gene ENSG00000156486.
Subcellular location: Cell membrane
Pathways (Reactome):
Neuronal System: Voltage gated Potassium channels
Gene Ontology:
Molecular function: protein binding; potassium channel regulator activity; monoatomic ion channel activity; voltage-gated potassium channel activity
Biological process: action potential; potassium ion transmembrane transport; potassium ion transport; regulation of potassium ion transmembrane transport; monoatomic ion transport; protein homooligomerization; transmembrane transport
Cellular component: membrane; perinuclear region of cytoplasm; plasma membrane; voltage-gated potassium channel complex; cytoplasm
Genetic constraint (gnomAD): Loss-of-function variants: 15 observed, 28.76 expected, observed/expected ratio (o/e) 0.52, 90% interval 0.35 to 0.8. The upper end of that interval is the gene's LOEUF score, 0.8, which puts it in group 3 of 6, group 1 being the genes least tolerant of losing a copy. Missense variants: 497 observed, 649.69 expected, observed/expected ratio (o/e) 0.76, 90% interval 0.71 to 0.82. Synonymous variants: 254 observed, 274.39 expected, observed/expected ratio (o/e) 0.93, 90% interval 0.83 to 1.03.
Homologues: Orthologues: chimpanzee KCNS2 (99% identical), macaque KCNS2 (99% identical), pig KCNS2 (99% identical), mouse Kcns2 (98% identical), rat Kcns2 (98% identical), rabbit KCNS2 (97% identical), dog KCNS2 (96% identical), guinea pig KCNS2 (92% identical), tropical clawed frog kcns2 (83% identical). Paralogues in human: KCNS3 (53% identical), KCNS1 (50% identical), KCNB2 (40% identical), KCNV1 (39% identical), KCNG1 (33% identical), KCNF1 (33% identical), KCNG4 (32% identical), KCNV2 (32% identical), KCNC3 (30% identical), KCNA10 (30% identical), KCND3 (30% identical), and 19 more.
Diseases named in the same sentence as KCNS2 in open-access papers:
KCNS2 is named in the same sentence as 6 diseases in open-access papers, as found by Europe PMC text mining. Sharing a sentence is not in itself a finding about the gene and the disease. The quoted sentences say what the papers report.
angiosarcoma (1 paper, 2016). A malignant tumor arising from the endothelial cells of the blood vessels. "Notably, expression of several potassium channels is modified in bladder cancer vessels vs controls (KCNC4, KCNG4, KCNS2) and in angiosarcoma vs controls (namely KCNJ16, KCNQ2, KCNJ15, KCNJ12, KCNJ1)." (PMID 27716384, 2016).
periodontitis (1 paper, 2024). An acute or chronic inflammatory process that affects the tissues that surround and support the teeth.
cancer (1 paper, 2022). A tumor composed of atypical neoplastic, often pleomorphic cells that invade other tissues.
KCNS2 also shares sentences with these, for which no sentence is quoted: bladder cancer (1 paper); ischemia (1); schizophrenia (1).